MYB (MYB proto-oncogene, transcription factor)
Diseases named in the same sentence as MYB in open-access papers (continued):
Sharing a sentence is not in itself a finding about the gene and the disease.
myelodysplastic syndrome (5 papers, 2022 to 2024). A clonal hematopoietic disorder characterized by dysplasia and ineffective hematopoiesis in one or more of the hematopoietic cell lines. "Flavopiridol was described as a MYB-downregulating CDK inhibitor that suppressed myelodysplastic syndrome and reduced myeloid cell numbers in MYB-hyperactivated zebrafish." (PMID 38835346, 2024). "This variant of MYB is haploinsufficient, and the patient carrying the mutant was a 30-year-old female with CVID and myelodysplastic syndrome, who eventually died of septic shock." (PMID 38028622, 2023).
non-small cell lung carcinoma (5 papers, 2013 to 2021). A group of at least three distinct histological types of lung cancer, including non-small cell squamous cell carcinoma, adenocarcinoma, and large cell carcinoma. "In non-small-cell lung cancer (NSCLC), miR-195 directly targets MYB 3'UTR and negatively regulates its expression, thereby regulating the proliferation and metastasis of tumor cells." (PMID 34876130, 2021). "In an attempt to expand the spectrum of potential MYB inhibitors we have discovered Bcr-TMP as a nanomolar-active MYB-inhibitory compound, which was described before as a potent caspase activator in human breast and non-small-cell lung cancer cells." (PMID 35008207, 2021).
oligodendroglioma (5 papers, 2017 to 2025). A well-differentiated (WHO grade II), diffusely infiltrating neuroglial tumor, typically located in the cerebral hemispheres. "Rearrangements and copy number abnormality in MYB or MYBL1 resulting in upregulated MYB or MYBL1 are found in more infiltrative pLGGs including grade 2 DAs, angiocentric gliomas and oligodendroglioma." (PMID 38318325, 2023). "This far, the mismatch sign has been reported in pilomyxoid astrocytoma, LGG harboring MYB rearrangement, oligodendroglioma (IDH-mut codel), and even in one patient with a non-neoplastic lesion." (PMID 32434559, 2020).
pilomyxoid astrocytoma (5 papers, 2020 to 2024). An astrocytic tumor of uncertain relation to pilocytic astrocytoma. "Similarly, although not strictly required, identification of MYB-QKI fusion can confirm a diagnosis of angiocentric glioma, which can be confused with other LGGs such as pilomyxoid astrocytoma, as evident in this series." (PMID 38764578, 2024).
gastric adenocarcinoma (4 papers, 2017 to 2025). "In vitro experiments demonstrated elevated mRNA expression of ERCC6L and MYB in human gastric adenocarcinoma AGS and HGC-27 cells compared to normal gastric epithelial GES-1 cells." (PMID 40672391, 2025). "Next, 10 ERGs associated with prognosis of gastric adenocarcinoma patients are screened out by univariate Cox regression, and 6 pivotal prognostic ERGs (MMP8, MMP11, TFDP3, MYB, F2, and CNTN1) are identified through multivariate Cox regression." (PMID 32309437, 2020). "Of these, 8 regions contained previously characterized amplified oncogenes: GATA4, CCND1, CDK6, MDM2, EGFR, MCL1, ERBB3 and MYB; this is the first report of significant and nearly isolated MYB amplification in gastric adenocarcinoma." (PMID 28426752, 2017).
iron deficiency (4 papers, 2021 to 2026). "Sixty-seven gene families were discovered to be involved in the control of iron deficiency stress by examining differentially expressed transcription factors, including the WRKY, MYB, AP2/ERF-ERF, bHLH, NAC, C2H2, bZIP, HB-HD-ZIP, and GARP-G2-like families." (PMID 35371147, 2022).
metastatic disease (4 papers, 2015 to 2025). "In a recent study, we identified c-Myb, a transcription factor and an oncoprotein encoded by MYB gene, as a negative prognostic factor in OSA patients associated with metastatic disease." (PMID 41345636, 2025).
renal carcinoma (4 papers, 2019 to 2023). A carcinoma arising from the epithelium of the renal parenchyma or the renal pelvis. "Here we show that MYBBP1A acts as a negative regulator of c-MYB, as loss of MYBBP1A leads to an increase of c-MYB activity in renal carcinoma cell lines." (PMID 30781655, 2019). "Another study revealed that in renal cancer MYB activated the transcription of miR-520h, which targeted MAGI1 and down-regulated its expression to suppress invasiveness and metastasis of tumor." (PMID 36994664, 2023). "MYBBP1A knock down in renal carcinoma cell lines results into an increase in c-MYB target genes expression, leading to an increase in the stem population." (PMID 30781655, 2019). "We have also found that MYBBP1A knock down increases the expression of CD34, NANOG and CXCR4, which are target genes of c-MYB, exclusively in renal carcinoma cell lines that express high levels of c-MYB." (PMID 30781655, 2019). "We identified that the downregulation of MYBBP1A increases tumorigenic properties, in vitro and in vivo, in renal carcinoma cell lines that express high levels of c-MYB exclusively." (PMID 30781655, 2019). "Therefore, we tested whether MYBBP1A also binds to c-MYB protein in our renal cancer cells by co-immunoprecipitation." (PMID 30781655, 2019). "We believe that the activation of c-MYB by MYBBP1A downregulation confer selective advantages over other tumor cells, leading to clinically relevant renal carcinoma tumors." (PMID 30781655, 2019). "After confirming that MYBBP1A was located in the nucleolus of renal cancer cells, as it has been described in other cell types, we observed co-localization of c-MYB and MYBBP1A in the nucleus, specifically nucleoli, of cells with high levels of c-MYB protein." (PMID 30781655, 2019). "We have observed the co-localization of MYBBP1A and c-MYB in the nucleolus of renal carcinoma cells and the co-immunoprecipitation of both proteins, which supports the hypothesis that MYBBP1A modulates c-MYB activity." (PMID 30781655, 2019). "Interestingly, exclusively renal cancer cell lines that express high levels of c-MYB and do not express pVHL can take advantage of this cellular increase in tumorigenesis." (PMID 30781655, 2019). "Interestingly, only renal cancer cell lines that express high levels of c‐MYB and do not express pVHL can take advantage of the cellular metabolism switch and increase tumorigenesis." (PMID 31066170, 2019).
acinic cell carcinoma (3 papers, 2020 to 2023). "Several genes that are known to be important in ACC tumors are highlighted with black dots at right, including (from top to bottom) EN1, GABRP, MYB, MYBL1 and NFIB, all of which are expressed more highly in the ACC tumors than in the normal salivary gland or acinic cell carcinoma samples (at left)." (PMID 36900183, 2023).
asthma (3 papers, 2011 to 2023). "From bioinformatic analysis and EMSA results, SNP rs6585018:G>A was found to affect binding of the transcription factor MYB with the A allele having a higher affinity for MYB compared with the allele G which is also the asthma risk allele in the present study." (PMID 23606399, 2013). "SNPs within MYB itself confer susceptibility to eosinophilia and asthma." (PMID 23606399, 2013). "We therefore propose that the PDCD4 protein and MYB-dependent regulation would be worthwhile for further investigation of its role in asthma-related mechanisms." (PMID 23606399, 2013).
brain tumors (3 papers, 2021 to 2022). "Recently, we also used cis-X to validate ASE patterns for two genes (TERT and MYB) with SV-associated altered expression by SVExpress in a cohort of pediatric brain tumors." (PMID 33743584, 2021).
COVID-19 (3 papers, 2022 to 2025). A disease caused by infection with severe acute respiratory syndrome coronavirus 2. "For example, TFs like STAT and E2F/MYB are associated with poor outcomes in severe COVID-19 due to their role in regulating inflammatory responses." (PMID 40919176, 2025). "Irrespective of the infection status, JQ-1 treatment suppressed activity of the TF families that regulate cell cycle and proliferation (E2F & MYB), whose synergistic signalling is associated with severe lung injury in COVID-19 cases." (PMID 37747932, 2023). "Since many of the genes regulated by MYB are involved in the cell cycle, anticancer drugs might serve as potential repurposed drugs for COVID-19." (PMID 35831333, 2022). "Hence, we propose MYB as a golden drug target for COVID-19 treatment." (PMID 35831333, 2022).
diabetes (3 papers, 2021 to 2023). "Moreover, it has been reported that c-MYB can regulate autophagy through activation of the p-AMPK/AKT pathway involved in the development of irreversible damage to the dental pulp due to diabetes and regulate cochlear hair cells from cisplatin-induced damage through the PI3K/AKT pathway." (PMID 37929023, 2023).
esophageal adenocarcinoma (3 papers, 2021 to 2025). A malignant tumor with glandular differentiation arising predominantly from Barrett mucosa in the lower third of the esophagus. "Although the genomic region of the candidate MYB-SE was also duplicated in esophageal adenocarcinoma (ESAD), a cancer type closely related in lineage but with remarkable biological differences compared to COREAD and STAD, the ChIP-seq analysis revealed that it did not constitute a SE (Fig. EV1E)." (PMID 40234694, 2025).
liver fibrosis (3 papers, 2019 to 2025). "By targeting MYB and inhibiting C-myb expression, this secretome suppresses NF-κB pathway activation and reduces the synthesis of type I collagen and alpha-smooth muscle actin, effectively impeding liver fibrosis progression." (PMID 40242037, 2025). "miR-150 and miR-194 inhibit the activation of hepatic stellate cells by inhibiting the expression of c-MYB and RAC1, leading to the reduction of collagen deposition in liver fibrosis." (PMID 31949877, 2019). "Given that an mRNA-based strategy has been developed to target HNF4A in preclinical models for liver fibrosis, similar strategy can be used to control the development of gastrointestinal adenocarcinoma with HNF4A-dependent overexpression of MYB." (PMID 40234694, 2025).
nematode infection (3 papers, 2021 to 2025). "In this study, we found that expression of genes encoding ERF (unigene 0004006) and MYB (unigene 0000628) transcription factors involved in plant hormone signaling was positively correlated with nematode infection." (PMID 34271854, 2021). "The role of the MYB genes in response to nematode infection is generally poorly understood and examined." (PMID 34208611, 2021). "More than half of these regulatory factors belong to the ZF, bZIP, bHLH, MYB, WRKY, and ERF families, suggesting key roles of these family members in regulating cellular-specific responses to nematode infection." (PMID 41209832, 2025).
prostate tumors (3 papers, 2022 to 2023). "Since Black men experience higher PCa incidence and mortality than White men, we examined if MYB was differentially expressed in prostate tumors from patients of these racial backgrounds." (PMID 38089573, 2023). "MYB expression was analyzed in prostate tumor tissues (n = 105), its adjacent BPH (n = 35), and HGPIN (n = 38) lesions by immunohistochemical analysis." (PMID 38089573, 2023). "To examine the significance of biphasic MYB regulation upon DHT treatment on prostate tumor cell growth, we silenced MYB expression by RNA interference prior to DHT treatment." (PMID 36410437, 2022). "Our observations also bring MYB and miR-150 to the forefront of prostate tumor biology by demonstrating their significance in the growth-stimulatory and growth-repressive effects of androgens." (PMID 36410437, 2022). "MYB not only reduces the motility of cancer cells but also slows down the secretion of cytokines and chemokines by cancer cells, showing a strong malignant phenotype in prostate tumors." (PMID 35164166, 2022). "Then, the activity of protein MYB demonstrates a strong malignant phenotype in prostate tumors." (PMID 35164166, 2022).
salivary carcinomas (3 papers, 2022 to 2025). "Molecular alterations in salivary gland carcinomas have been studied, including the CRTC1-MAML2 and MYB-NFIB fusion genes found in MEC and ACC, respectively." (PMID 40192115, 2025). "MYB–NFIB fusion has not been detected in other salivary carcinomas to our knowledge." (PMID 39199639, 2024).
spiradenomas (3 papers, 2016 to 2022). "In MYB‐positive spiradenomas, the expression was also variable in intensity, with positive cells scattered throughout the specimens." (PMID 26969893, 2016).
/T-cell lymphoma (2 papers, 2016 to 2022). "It has indeed been shown that the miR-150 target gene repertoire can highly differ between different hematopoietic malignancies, e.g., MYB, FLT3, CBL and EGR2 in MLL-rearranged AML cells, and DKC1 and AKT2 in NK/T-cell lymphoma." (PMID 35205272, 2022). "MYB, FLT3, and EGR2 have been identified as critical target genes of miR-150 in MLL-rearranged AML, while AKT2 is a direct target of miR-150 in NK/T-cell lymphoma." (PMID 27917123, 2016).
acute leukemia (2 papers, 2018 to 2024). A clonal (malignant) hematopoietic disorder with an acute onset, affecting the bone marrow and the peripheral blood. "MYB is an important hematopoietic transcription factor involved in proliferation as well as differentiation and upregulated in most human acute leukemias." (PMID 29854289, 2018). "MYB fusions are recurrently found in select cancers, including blastic plasmacytoid DC neoplasm (BPDCN), an acute leukemia with poor prognosis." (PMID 39499902, 2024).
adenoma (2 papers, 2014 to 2020). A neoplasm arising from the epithelium. "Upregulated MYB expression has already been reported in human and mouse colorectal tumors, including adenomas." (PMID 24472434, 2014).
diffuse large B-cell lymphoma (2 papers, 2022 to 2024). "The cytotoxicity of the Ras-mimetic PI3K/PLK1 inhibitor rigosertib in diffuse large B-cell lymphoma (DLBCL) cells was associated with MYB suppression and inhibition of nuclear MYB translocation by sumoylation." (PMID 38835346, 2024). "Here we studied the relevance of the MYC/miR-150/MYB/ZDHHC11 network in two other GC B-cell derived lymphomas, i.e., Hodgkin lymphoma (HL) and diffuse large B-cell lymphoma (DLBCL)." (PMID 35205272, 2022).
endometrial cancer (2 papers, 2022 to 2023). Primary or metastatic malignant neoplasm involving the endometrium (mucous membrane that lines the endometrial cavity). "METTL14 promotes tumorigenesis by upregulating expression of MYC and MYB in acute myelocytic leukaemia (AML) but acts as a tumor suppressor by inactivating AKT in endometrial cancer." (PMID 35047058, 2022).
eosinophilia (2 papers, 2013 to 2025). "STAT5 signaling, particularly in response to TSLP, has a crucial role in promoting Th2-mediated inflammation and eosinophilia, whereas MYB promotes T cell differentiation and hematopoietic cell proliferation." (PMID 40470207, 2025).
lymphoid neoplasm (2 papers, 2019 to 2021). A neoplasm composed of a lymphocytic cell population which is usually malignant (clonal) by molecular genetic and/or immunophenotypic analysis. "dup(1q)/gain of CKS1B, del(6q)/deletion of MYB, and del(9p)/deletion of CDKN2A, which are common in lymphoid neoplasms, were detected at a low frequency in adult B‐ALL patients with hyperdiploidy." (PMID 31173486, 2019).
malignant neoplasms of the salivary glands (2 papers, 2024 to 2025). "Salivary gland cancer organoids recapitulated the parental tissue genotypic characterization, with >97.6% of all COSMIC annotated variants and all MYB, MYBL1, and NFIB gene rearrangements retained." (PMID 39309690, 2024).
multiple myeloma (2 papers, 2021 to 2024). "LiCl and SB216763, both inhibitors of the serine/threonine glycogen synthase kinase 3β (GSK3β), were antiproliferative against Jurkat (acute T-cell leukemia), K562 (CML), and RPMI-8226 (myeloma) cells by promotion of proteasomal MYB degradation and suppression of BCL2, survivin, and MYC." (PMID 38835346, 2024). "The PROTAC ARV-825 was antiproliferative in a panel of 13 multiple myeloma (MM) cell lines, led to cell cycle arrest and apoptosis, and quickly degraded BRD2 and BRD4 accompanied by suppression of MYB and MYC." (PMID 38835346, 2024).
myelofibrosis (2 papers, 2016 to 2022). A partial or complete replacement of the bone marrow stroma by fibrous tissue. "This fusion has been described before in a myelofibrosis case and is believed to lead to upregulation of MYB." (PMID 36077692, 2022).
myeloid neoplasm (2 papers, 2016 to 2017). Proliferation of myeloid cells originating from a primitive stem cell. "High levels of MYB mRNA were also detected in 2 out of 4 human myeloid neoplasms with SETBP1 missense mutations." (PMID 27863435, 2016). "Identification of Myb as a critical target of wild-type and mutant Setbp1 in our study suggest that inhibition of MYB could be a potential strategy for treating myeloid neoplasms with SETBP1 activation." (PMID 27863435, 2016). "Furthermore, the finding of interplay between MYB and mutant or wild type SETBP1 suggests that MYB inhibition could be a promising approach for treating myeloid neoplasms with SETBP1 activation." (PMID 28881700, 2017).
nasopharyngeal carcinoma (2 papers, 2015 to 2018). A carcinoma arising from the nasopharyngeal epithelium. "Consistent with this view, recent studies have demonstrated that in EBV-infected nasopharyngeal carcinoma cell lines, NFκB signaling regulates MYB expression." (PMID 25853889, 2015).
renal cell carcinoma (2 papers, 2019 to 2021). "Finally, loss of MYBBP1A is observed in a significant percentage of patients with renal cell carcinoma, who show a metastatic tendency and poor prognosis, probably due to the increased stem phenotype caused by c-MYB activation." (PMID 30781655, 2019). "At the same time, MYB promotes the transcriptional activity of miR-520-h by binding to the RCC promoter to regulate MAGI1 expression, and the overexpression or knockout of MAGI1 regulates PETN/MAGI1/β-Catenin and significantly affects the invasion and migration of human renal cell carcinoma cells." (PMID 34876130, 2021).
Stroke (2 papers, 2021 to 2024). Sudden impairment of blood flow to a part of the brain due to occlusion or rupture of an artery to the brain. "MiR-150 and its target MYB can form a negative feedback loop to control the level of post-stroke vascular endothelial growth factor (VEGF) expression." (PMID 38653998, 2024). "In this work, we demonstrate that microRNA-150 (miR-150) and its predicted target MYB form a negative feedback loop to control the level of post-stroke VEGF expression." (PMID 33815136, 2021).
triple-negative breast carcinoma (2 papers, 2022 to 2025). An invasive breast carcinoma which is negative for expression of estrogen receptor (ER), progesterone receptor (PR), and human epidermal growth factor receptor 2 (HER2). "Additionally, MYB expression by IHC has been observed in up to 63% of other basal-like, triple negative breast cancers and is not pathognomonic for SB-AdCC11." (PMID 35953528, 2022).
acute basophilic leukemia (1 paper, 2022). A rare acute myeloid leukemia in which the immature cells differentiate towards basophils. "MYB may play a key role in the leukemic transformation process, similar to MYB::GATA1 rearrangements in acute basophilic leukemia." (PMID 36077669, 2022).
albinism (1 paper, 2023). A congenital disorder characterized by partial or complete absence of melanin pigment in the eyes, hair, or skin. "Chlorophyllase 2, Chlorophyll a-Binding Protein 4A, Chlorophyll a-Binding Protein 24, Stay Green Regulator, Photosystem II Cytochrome b559 subunit beta along with transcription factors AP2, bZIP, MYB, and WRKY were identified as a potential regulator of albinism in Yanling Yinbiancha." (PMID 37745858, 2023).
amoebiasis (1 paper, 2018). "In Entamoeba histolytica, the causative protozoan of human amoebiasis, the MYB DBD is the most abundant domain related to transcriptional regulation." (PMID 30333961, 2018).